MRPL40 (mitochondrial ribosomal protein L40)
Synonyms: L40mt; MRP-L40; NLVCF; URIM; MRP-L22; mL40
Tractability: Small molecule: a structure with a bound ligand is known. PROTAC: ubiquitination databases record sites on it; its protein half-life has been measured.
Gene: Protein-coding gene on chromosome 22 (19,432,467 to 19,436,077, forward strand). Ensembl gene ENSG00000185608.
Subcellular location: Mitochondrion
Subcellular location (Human Protein Atlas): Mitochondria; Nucleoli
Pathways (Reactome):
Metabolism of proteins: Mitochondrial ribosome-associated quality control; Mitochondrial translation elongation; Mitochondrial translation initiation; Mitochondrial translation termination
Gene Ontology:
Molecular function: protein binding; RNA binding
Biological process: anatomical structure morphogenesis; mitochondrial translation
Cellular component: mitochondrial large ribosomal subunit; mitochondrion; mitochondrial inner membrane; mitochondrial ribosome; nucleus
Genetic constraint (gnomAD): Loss-of-function variants: 14 observed, 19.15 expected, observed/expected ratio (o/e) 0.73, 90% interval 0.48 to 1.14. The upper end of that interval is the gene's LOEUF score, 1.14, which puts it in group 5 of 6, group 1 being the genes least tolerant of losing a copy. Missense variants: 214 observed, 214.61 expected, observed/expected ratio (o/e) 1, 90% interval 0.89 to 1.12. Synonymous variants: 95 observed, 81.61 expected, observed/expected ratio (o/e) 1.16, 90% interval 0.99 to 1.38.
Homologues: Orthologues: chimpanzee MRPL40 (98% identical), macaque MRPL40 (91% identical), guinea pig MRPL40 (81% identical), rat Mrpl40 (76% identical), mouse Mrpl40 (75% identical), rabbit MRPL40 (75% identical), dog MRPL40 (75% identical), pig MRPL40 (72% identical), tropical clawed frog mrpl40 (49% identical), zebrafish mrpl40 (45% identical), Drosophila melanogaster mRpL40 (33% identical), Caenorhabditis elegans mrpl-40 (27% identical).
Diseases named in the same sentence as MRPL40 in open-access papers:
MRPL40 is named in the same sentence as 11 diseases in open-access papers, as found by Europe PMC text mining. Sharing a sentence is not in itself a finding about the gene and the disease. The quoted sentences say what the papers report.
psychosis (2 papers, 2019 to 2022). "In support of this, transgenic mice lacking one copy of Mrpl40 show alterations in mitochondrial calcium and exhibited psychosis-related cognitive deficits." (PMID 36527106, 2022).
Alzheimer disease (1 paper, 2015). A progressive, neurodegenerative disease characterized by loss of function and death of nerve cells in several areas of the brain leading to loss of cognitive function such as memory and language. "For example, MRPL40 knockouts in the fruit fly show defects in neurogenesis that compromise neurodevelopment, and knockdowns of TXNRD2 in worms overexpressing human beta-amyloid peptide as a model for Alzheimer’s disease were more susceptible to muscular dysfunction and paralysis." (PMID 26137170, 2015).
colon cancer (1 paper, 2021). "Finally, the GTPase ERAL1, mitochondrial ribosomal proteins ERAL1, MRPL11, MRPL15, MRPL30, MRPL37, MRPL40, and MRPL52 were determined to be hub proteins with a commonly down-regulated trend in four berberine-treated colon cancer cell lines." (PMID 33806918, 2021).
hepatoma (1 paper, 2013). "Cellular fractionation experiments demonstrated a decreased mitochondrial pool of Mrpl40 after TCDD treatment in AHR expressing hepatoma cells." (PMID 24454361, 2013).
rectal cancer (1 paper, 2025). A primary or metastatic malignant neoplasm that affects the rectum. "Moreover, the downregulation of MRPL40 expression can eliminate the effect of interleukin-8 (IL-8) on promoting the proliferation and migration of rectal cancer." (PMID 40344088, 2025).
tumor (1 paper, 2024). "In contrast, six genes known to inhibit cell proliferation and tumor growth were overexpressed in d-HGP: SIRT6, MPC2, MIR4458HG, ST20-AS1, SREBF2, MRPL40." (PMID 38548918, 2024).
MRPL40 also shares sentences with these, for which no sentence is quoted: atherosclerosis (1 paper); cognitive deficits (1); cryptorchidism (1); microcephaly (1); neurodevelopmental disorder (1).